CBS (cystathionine beta-synthase)
Diseases named in the same sentence as CBS in open-access papers (continued):
Sharing a sentence is not in itself a finding about the gene and the disease.
tumor (continued). "Moreover, the absence of CBS blocked the density and convolution of CD31-positive vessels between the tumor tissues, indicating reduced tumor angiogenesis." (PMID 35684331, 2022). "Thus, elevated expression of cystathionine-beta-synthase and glutamate cysteine ligase modifier GCLM were observed in Bezielle treated tumor cells but not in non-transformed cells." (PMID 22319564, 2012). "Interestingly, in KRASMut and WT tumor samples, a correlation was observed between CBS and CTH genes expression, corresponding to A549 and H292 genetic background, while the expression of CBS and CTH were not correlated in PC-9 cells (EGFRMut)." (PMID 38247476, 2023).
metabolic disorder (15 papers, 2010 to 2025). "It is an inborn error of metabolism with high clinical variability resulting in a metabolic disorder due to deficiency in cystathionine beta-synthase CBS enzyme activity." (PMID 32245022, 2020). "CBS-deficient homocystinuria (CBSDH) is an autosomal recessive metabolic disease, resulting from inactivating mutations in the CBS gene." (PMID 30050925, 2018). "Cystathionine beta-synthase (CBS) deficiency (CBSD), also known as classical homocystinuria (HCU; OMIM 236200), is an autosomal recessive metabolic disorder of sulfur metabolism due to variations on CBS located on chromosome 21q22.3." (PMID 36832525, 2023).
cardiovascular disease (13 papers, 2012 to 2025). "The presence of an additional copy of genes on chromosome 21 (i.e., the superoxide dismutase 1 gene (SOD1) and gene coding for the cystathionine β-synthase (CBS) enzyme) raises the risk for cardiovascular disease (CVD)." (PMID 36551975, 2022). "The majority of B6 non-responders presented ocular and skeletal disorders, while CBS-deficient B6 responders presented skeletal and cardiovascular disorders, followed by ocular complications." (PMID 30871635, 2019). "More researches are needed to understand the role BHMT rs10037045 plays in atherogenesis and cardiovascular diseases, and its interaction with CBS rs2851391." (PMID 27822905, 2017). "Another study concluded that while lowering homocysteine levels in CBS-deficient patients, it was not clear if lowering levels in patients with cardiovascular disease of unknown origin was beneficial." (PMID 39583366, 2024).
infection (13 papers, 2012 to 2025). The state of being infected such as from the introduction of a foreign agent such as serum, vaccine, antigenic substance or organism. "In addition, infections with Gag CBS variants induced a redistribution of integration sites along the host genome with a marked preference of the Gag Y573Q virus to target late-replicating chromosomes." (PMID 40448500, 2025). "Of note, hypoxia insult suppresses CSE expression but not CBS expression in adrenal glands, while LPS treatment results in a decrease in both of CBS and CSE expression in adrenal glands, which suggests that CSE and CBS expression is susceptible to detrimental insults such as hypoxia and infection." (PMID 36661247, 2023). "The present study addressed how physical exercise interacts with the immune system by assessing fever (the hallmark of infection), the preoptic production rate of H2S, the protein expression of the H2S-related enzymes CBS, 3-MPST and CSE, and plasma levels of cytokines and CORT." (PMID 28118407, 2017). "If the delayed chromatin tethering observed with CBS mutants delayed integration, the kinetics of infection should be differentially sensitive to DTG treatment." (PMID 40448500, 2025). "While many studies suggest the potential of CBs in controlling host responses to bacterial infections, outcomes vary depending on the specific infection, cannabinoid, and cannabinoid receptor involved." (PMID 38775488, 2024). "And we noticed that CBS levels increased significantly within 3–4 h of infection and both CBS and 3-MPST protein decreased within 5–6 h." (PMID 37644526, 2023). "Infection of RAW 264.7 macrophages with Mtb H37Rv resulted in a 34-fold increase in the level of CBS, a major enzymatic source of H2S in mammalian cells." (PMID 31992699, 2020). "Mtb infection of murine macrophages led to increased expression of CBS as early as 6 h post-infection." (PMID 33330130, 2020). "Lungs samples were harvested at day 1 post-infection to assess mRNA levels of catalase, Cu/Zn-superoxide dismutase (SOD1), CSE, CBS, and 3-MST." (PMID 29740449, 2018). "Interestingly, following infection, the production of CSE increased in the WT, whereas the production and transcription of CBS increased in both the WT and CSE−/− macrophages, with significantly greater CBS expression in the infected CSE−/− macrophages." (PMID 32139610, 2020). "Infection of Cbs+/+ (WT) peritoneal macrophages resulted in a 25-fold increase in the level of CBS, whereas the levels of CSE and 3-MST did not change appreciably." (PMID 31992699, 2020). "Hrp1 is a secreted protein with two cystathionine beta synthase (CBS) domains but its biological function and role in infection is also unknown." (PMID 28505176, 2017). "Depletion of CBS was obtained by lentiviral CBS-targeting shRNA, whereas infection with empty vector or a non-targeting shRNA (data not shown) did not affect CBS levels." (PMID 23117410, 2012).
neurodegenerative disease (7 papers, 2017 to 2023). A disorder of the central nervous system characterized by gradual and progressive loss of neural tissue and neurologic function. "The body regulates CBS, 3MST, and CSE levels in the CNS, and higher or lower levels of these enzymes cause various neurodegenerative diseases." (PMID 29507650, 2018). "However, a decrease in the expression of H2S producing enzyme (primarily CSE, but also CBS and MPST) and consequently the loss of persulfidation were found in aging and different age-induced diseases, such as neurodegenerative diseases." (PMID 37288744, 2023). "The cytoprotective effect of H2S as a signaling molecule against ROS, as well as cell-specific enzymatic activities (e.g., CBS, CSE, and 3MST), may add further protection against neurodegenerative diseases." (PMID 31692944, 2019).
renal disease (6 papers, 2014 to 2023). "Additionally, the importance of 3-MST/H2S pathway is also suggested by the fact that ROS, the common cause of renal diseases of all types, induces the translocation of CBS and CSE into mitochondria." (PMID 27803669, 2016). "Several studies have revealed low levels of CBS, CSE, and 3-MPST in various renal diseases and demonstrated that H2S donor treatments can effectively improve the disease states." (PMID 33364941, 2020). "Low production of H2S and downregulation of CBS, CSE, and 3-MPST expressions have been reported in common renal disorders." (PMID 33364941, 2020). "In contrast to the extensive studies on CBS and CSE in various kidney diseases, the role of 3-MST is largely neglected although definitive evidence has demonstrated its abundance in kidney." (PMID 27803669, 2016).
adenocarcinoma (3 papers, 2023 to 2024). A common cancer characterized by the presence of malignant glandular cells. "We described the CBS important role in the hydrogen sulfide metabolism in the adenocarcinoma MCF-7 cell line." (PMID 38397425, 2024). "In PCa cell lines, CBS protein was highest in the LNCaP, C4-2, 22Rv1, and CWRR1 adenocarcinoma lines." (PMID 38172561, 2024).
heart disease (3 papers, 2021 to 2025). "One patient developed seizures and another experienced ischaemic heart disease during the follow‐up period and they were siblings with the CBS, c.19del variant." (PMID 39839200, 2025).
myopathy (2 papers, 2015 to 2022). A disease of the muscle in which the muscle fibers do not function properly. "Although skeletal muscles express the key enzyme (MTHFR) that participate in re-methylation of Hcy into methionine, lack of trans-sulfuration enzymes (CBS and CSE) make skeletal muscles more susceptible to the HHcy-induced myopathy." (PMID 25608649, 2015). "Although skeletal muscles express the key enzyme (MTHFR) that participates in re-methylation of Hcy into methionine, lack of trans-sulfuration enzymes (CBS and CSE) make skeletal muscles more susceptible to the HHcy-induced myopathy." (PMID 25608649, 2015).
connective tissue disorder (1 paper, 2010). A disease involving the connective tissue. "Inactivation of CBS results in CBS-deficient homocystinuria more commonly referred to as classical homocystinuria, which, if untreated, results in mental retardation, thromboembolic complications, and a range of connective tissue disorders." (PMID 20638879, 2010).
gastrointestinal disorders (1 paper, 2015). "The present study suggest the modification of CBS-derived H2S pathway is a useful alternative strategy for the treatment of FD-related gastrointestinal disorders." (PMID 26531221, 2015).
gastrointestinal tumor (1 paper, 2012). "To contrast CBS expression in normal tissues to malignant cells, we analyzed gastrointestinal tumor cell lines." (PMID 23152928, 2012).
inflammation (1 paper, 2014). Aberrant reaction of the microcirculation characterized by movement of fluid and leukocytes from the blood into extravascular tissues. "Injection of a CBS inhibitor reduced excitability of TG neurons in rats with TMJ inflammation induced by CFA injection." (PMID 24490955, 2014).
peripheral neuropathy (1 paper, 2024). A disorder affecting the peripheral nervous system. "Through MR analysis, we identified eight proteins (UBC12, SEM4C, IL_23_R, prothrombin, CBS, Microglobulin, MATN4, and COLEC12) with causal relationships to peripheral neuropathy." (PMID 39268072, 2024).
CBS also shares sentences with these, for which no sentence is quoted: brain injury (4 papers); Thromboembolism (3); acute myeloid leukemia (2); astrocytoma (2); diabetic cardiomyopathy (2); enteritis (2); frontotemporal dementia (2); genetic disorder (2); head and neck squamous cell carcinoma (2); hemorrhagic stroke (2); kidney damage (2); metabolic dysfunction-associated steatotic liver disease (2); multiple system atrophy (2); myocardial infarction (2); Pectus excavatum (2); renal failure (2); abdominal aortic aneurysm (1); alcoholism (1); amino acid metabolism disorder (1); anencephaly (1); angiosarcoma (1); Aortic dissection (1); Arthritis (1); arthropathy (1); asthenospermia (1); autosomal recessive deafness (1); autosomal recessive disease (1); B-cell acute lymphoblastic leukemia (1); bacterial infections (1); benign hyperplasia prostate (1).
A further 105 diseases each share a sentence with CBS in 1 paper.